LINC00278 (long independently transcribed non-coding RNA 278)
Synonyms: YY1BM; NCRNA00278
Gene: Long non-coding RNA gene on chromosome Y (3,002,887 to 3,200,509, forward strand). Ensembl gene ENSG00000231535.
Diseases named in the same sentence as LINC00278 in open-access papers:
LINC00278 is named in the same sentence as 1 disease in open-access papers, as found by Europe PMC text mining. Sharing a sentence is not in itself a finding about the gene and the disease. The quoted sentences say what the papers report.
esophageal squamous cell carcinoma (2 papers, 2025). Esophageal squamous cell carcinoma (ESCC) is a type of esophageal carcinoma (EC) that can affect any part of the esophagus, but is usually located in the upper or middle third. "Wu and colleagues discovered a Yin Yang 1-blocking polypeptide (YY1BM), which is encoded by lncRNA LINC00278 on the Y chromosome and has a lower expression in esophageal squamous cell carcinoma (ESCC) than in adjacent normal tissues." (PMID 41291707, 2025).